PAK1 (p21 (RAC1) activated kinase 1)
Diseases named in the same sentence as PAK1 in open-access papers (continued):
Sharing a sentence is not in itself a finding about the gene and the disease.
cancer (continued). "LIMK1 is a crucial component of Rac1/PAK1/LIMK1/cofilin signaling pathway, which is involved in several cancers." (PMID 34149814, 2021). "RAC1 is a key regulator of multiple oncogenic pathways including activation of mTORC1/2, PAK1/2/3 and MAPK signaling, which plays an important and critical role in cancer metastasis and cell survival." (PMID 34803511, 2021). "Thus, PAK1 inhibition might be a potential option for NF-κB-dependent cancer therapy." (PMID 33796531, 2021). "PAK1 and PAK4, for instance, are of particular interest in cancer biology due to their involvement in tumor formation and upregulation in various cancer types." (PMID 36594908, 2021). "More importantly, CAPE, CA, and ARC show significant therapeutic effects on various diseases, such as cancers, infectious diseases (HIV, HPV, influenza virus, and so on), inflammatory diseases, and PAK1-dependent MR (AD, PD, and HD), as well as T2DM." (PMID 33796531, 2021). "Increasing evidence has demonstrated that high expression of PAK1 was observed in various cancers including ESCC, and PAK1 played an crucial role in regulating tumour growth and metastasis." (PMID 32237037, 2020). "Numerous studies have confirmed that the PAK1-regulated pathway network contributes to EMT and metastasis in multiple types of cancer." (PMID 32863957, 2020). "Amongst the PAK family members, PAK1 and PAK4 are the most studied in human cancers, due to their central roles in many oncogenic signaling pathways, and they have emerged as potential therapeutic targets in cancer." (PMID 32863957, 2020). "PAK1-regulated STAT3-NF-κB signaling continues to activate the inflammatory response, and the releases of IL-1α and IL-18 will induce cancer cell proliferation, survival, and immunosuppression." (PMID 32863957, 2020). "The phosphorylation of Raf on Serine 338 by PAK1 promotes its kinase activity to activate cell cycle checkpoint kinase 2 (CHK2) to regulate the DNA damage response, which contributes to cancer cell survival." (PMID 32863957, 2020). "Upregulation of the metabolic genes (ALDH18A1, CAD, CHKA, POLD4, PSPH, and SQLE) and aberrant expression of cancer-related genes (ALCAM, ITGA6, DDIT3, MAP3K6, and PAK1) were found in mouse fed with high-fat-high-cholesterol similar to human NASH-HCCs." (PMID 31795276, 2019). "RAC1 controls cancer cell invasion by regulating the production of matrix metalloproteinases, MMPs (RAC1/PAK1/p38/MMP-2 axis regulated angiogenesis), and their natural inhibitors, the tissue-specific inhibitors of MMP (TIMPs)." (PMID 31027363, 2019). "PAK1 regulates cofilin and MLC phosphorylation at sites of invadopodium degradation during disassembly, which has functional consequences during cancer cell extravasation, a key step of the metastatic cascade." (PMID 30651600, 2019). "Accumulating data show that PAK1, PAK3, and PAK4 regulate cell proliferation, motility, and angiogenesis in several types of cancer cells." (PMID 31658701, 2019). "We also confirmed the cancer promoting role of very rare helpers, including ABI2, NCOR2 and PAK1 that are altered in 1–4% of EACs." (PMID 31308377, 2019). "The tumor suppressor Nischarin interacts with a number of signaling proteins such as Integrin α5, PAK1, LIMK1, LKB1, and Rac1 to prevent cancer cell migration." (PMID 29415725, 2018). "We demonstrated for the first time the aberrant expression of cancer-related genes (ALCAM, ITGA6, DDIT3, MAP3K6 and PAK1) and metabolism-related genes (ALDH18A1, CAD, CHKA, POLD4, PSPH, SQLE and CFD) in human NASH-HCCs." (PMID 30367044, 2018). "For all other hallmarks of cancer features promising prognostic biomarkers were identified as well, including COX-2, PAK-1, p14ARF, MET, LC3B, IGFBP7 and LGR5." (PMID 30185893, 2018). "To date, it has been well established that miR-7 directly targets many oncogenic factors and is involved into multiple cancer-related signalling pathways, including EGFR, IRS-1/2, Raf1, Pak1, Ack1, PA28-gamma, IGF1R, PIK3CD and mTOR32–38." (PMID 28710406, 2017).
cancer (continued). "The data presented here complements previously published studies with other cancer types and suggests a global involvement for PAK1 and PAK4 in cancer invasion at least in vitro." (PMID 27765920, 2016). "Along this line, the fact that we found the C-terminal polyproline-rich region of 28 amino acids to be responsible for binding to PAK1 may provide a starting point for evaluating peptide-based inhibitors that block the Rac1 signaling pathway in endometrial and possibly other types of cancers." (PMID 27760566, 2016). "Rac1 activation results in PAK1 phosphorylation, which leads to cytoskeletal remodeling, alterations in cell adhesion, as well as the EMT, all of which are required for promoting cancer cell migration." (PMID 25860930, 2015). "Similarly, PAK1 overexpression induced lamellipodia and filopodia formations in quiescent Swiss 3T3 cells, increased cell motility via destabilization of actin stress fibres and the increase of focal adhesions turnover, suggesting its role in cancer metastasis." (PMID 25093037, 2014). "Although the mechanism by which IPA-3 induces the apoptosis of HCC cells is not completely known, PAK1 has been shown to phosphorylate the anti-apoptotic protein, BAD, to suppress the apoptosis of cancer cells." (PMID 23894351, 2013). "Previously known targets for miR-7 include messages for signaling proteins, Pak1 and epidermal growth factor receptor (EGFR), known to be activated in many forms of cancer." (PMID 21454924, 2011). "An important consideration in our discussion is the targeting of PAK1/Hippo in therapeutic approaches in cancer therapy, often without discussion of off‐target effects inducing dysfunction in the heart, adipose tissue, and β‐cells." (PMID 40065530, 2025). "The possible apoptotic pathways for anti-cancer effects of curcumin on cell signal transduction include PI3K, Akt, mTOR, ERK5, AP-1, TGF-β, Wnt, β-catenin, Shh, PAK1, Rac1, STAT3, PPARγ, EBPα, NLRP3 inflammasome, p38MAPK, Nrf2, Notch-1, AMPK, TLR-4, and MyD-88." (PMID 41149437, 2025). "Furthermore, PAK1 activity is reportedly elevated in UM, where it, along with PAK4, contributes to the invasiveness of the cancer cells." (PMID 41154654, 2025). "The concept of modulating PAK1 rather than completely inhibiting it is emerging as a refined therapeutic approach to attenuate aberrant cancer signaling." (PMID 40001545, 2025). "Among the PAK isoforms, PAK1 and PAK4 are the most extensively studied in cancers." (PMID 40943273, 2025). "Considering that interference with PAK1 function makes at least some BRAF- and RAS-driven cancer cells more vulnerable to the inhibitors of the MAPK cascade, we tested whether inhibition of RAC would have a similar effect." (PMID 41465386, 2025). "We found that PAK1 knockout reduced tumour growth and new blood vessel formation while improving vessel normalisation, whereas PAK4 knockout increased vessel diameter and sensitised cancer cells to chemotherapy." (PMID 41228228, 2025). "PAK1 and its eponymous activator RAC1 (also known as p21RAC1) are important components of signaling by oncogenic RAS proteins and represent a targetable vulnerability in cancer cells driven by RAS oncogenes." (PMID 41154654, 2025). "PAK1 (p21-activated protein kinase) and its eponymous activator RAC1 (also known as p21RAC1) are important components of signaling by oncogenic RAS proteins and represent a targetable vulnerability in cancer cells driven by RAS oncogenes." (PMID 41465386, 2025). "Moreover, the VEGFA expression, a key pro-angiogenic factor in cancer cells, was markedly reduced in PAK1KD cells, suggesting a reduced angiogenic potential following PAK1 suppression." (PMID 41294859, 2025). "As epithelial-mesenchymal transition is the initial step for cancer invasion and metastasis, we decided to test whether PRL-activated PAK1 participates in EMT." (PMID 38660565, 2024).
cancer (continued). "However, the current research and the development of inhibitors for the clinical applications of PAK1 and PAK2 in the vascular field are relatively limited, and most studies have focused on their role in cancer and neurological diseases." (PMID 39766303, 2024). "Notably, we observed that chronic treatment with LDOPA had opposing effects on the expression of PAK1, a known activator of the MAPK pathway and a breast cancer oncogene." (PMID 40144773, 2024). "Indeed, we observed that the inhibition of ECM endocytosis by PAK1 knock-down and the blockade of tyrosine catabolism by HPDL down-regulation opposed cancer cell migration and invasion in 3D system." (PMID 38227562, 2024). "By inhibiting PAK1, ATRA may block a key node in multiple signalling networks that are required by many cancers and thus suppress cancer growth and enhance the inhibitory effects of other anticancer agents, such as Sorafenib." (PMID 37537668, 2023). "Altogether these results demonstrate that RAB7A regulates AKT and PAK1 kinases, affecting their downstream effectors and the processes they regulate, suggesting that RAB7A could have a role in a number of cancer hallmarks." (PMID 34066419, 2021). "Besides, PAK1 phosphorylates Raf at S338 to activate checkpoint kinase 2 (CHK2), leading to DNA damage response and cancer cell survival." (PMID 33796531, 2021). "Increased PAK1 and PAK4 expression in ES is consistent with those seen in other cancer types." (PMID 36594908, 2021). "PAK1 phosphorylates β-catenin at S675 and S663 to stabilize β-catenin and translocate to nuclear, activating transcription of targeted genes, containing c-MYC, CCND1, and MMP, leading to promoted cancer progression and drug resistance." (PMID 33796531, 2021). "The co-inhibition of PAK1 and other core proteins in the network, such as AKT and MEK, may also become a new strategy for cancer treatment." (PMID 32863957, 2020). "In contrast, PAK1 and CDK1 were much more abundant in cancer cells compared to stromal cells." (PMID 32917870, 2020). "PAK1 stimulates cancer cell proliferation and survival via ERK- and AKT-dependent pathways, and both ERK- and AKT-dependent pathways are involved in the anti-proliferation and pro-apoptosis of cancer cells by cannabinoids." (PMID 33126623, 2020). "The role of PAK1 in EMT and metastasis has been a hot topic in the field of cancer." (PMID 32863957, 2020). "In Proteoglycans in cancer pathway, FZD9, GPC1, PAK1, FZD1, and ACTB were extracted." (PMID 30733969, 2019). "While our data suggest that PAK‐1 is a promising potential therapeutic target for some cancers, the IC50 value of IPA‐3 (~15 μM) is not optimal for clinical translation." (PMID 31516713, 2019). "Previously, our group worked with OP and reported that it directly inhibits the major oncogenic kinase, p21-activated kinase 1 (PAK1), and hence, it is suggested to be utilized as a potent herbal drug for treating cancer, hyperpigmentation, and for extending the lifespan." (PMID 30262742, 2018). "Furthermore, interrogation of signaling partners in the NF2 cascade revealed high levels of PAK1, an upstream oncogene that inactivates NF2 in cancer cells through phosphorylation." (PMID 28552950, 2017). "Therefore, the down-regulation of FA/BRCA genes mediated by PAK1 creates a state of “FA/BRCAness”, and represents a rational approach for expanding the efficacy of PARP inhibitors to FA/BRCA-proficient cancer populations." (PMID 27740936, 2016). "In previous study, the relationship between RUFY3 and PAK1 pathways in cancer has not been described." (PMID 25766321, 2015). "Moreover, both PAK1 and HRAS are involved in transduction of proliferation signals and their miss-regulation leads to abnormal signal transduction and cancer." (PMID 25965968, 2015). "Immunoblot analysis and data mining demonstrated that PAK1 protein and mRNA were upregulated in cancer tissues compared to the noncancerous tissues." (PMID 24236193, 2013).
cancer (continued). "Overexpression or activation of PAK1 has been reported in a large number of malignancies and, not surprisingly, this kinase is recognized a potential target for cancer therapy." (PMID 22869096, 2012). "By targeting accessory proteins involved in PAK1 regulation and modulation, it may be possible to fine-tune PAK1 activity, reducing cancer invasion and drug resistance without fully blocking essential cellular processes." (PMID 40001545, 2025). "miR-15b exerts its effects in these cancers through various mechanisms, such as the regulation of proliferation, apoptosis, epithelial–mesenchymal transition (EMT), and drug resistance, mediated by the NF-κB, STAT3, AKT/mTORC1, CDC42/PAK1, and β-catenin signalling pathways." (PMID 39456841, 2024). "In addition, PAK1 is a key downstream effector of Small Rho GTPases Rac1 and CDC42 and which was related to cell morphogenesis, motility, mitosis, survival, and angiogenesis in various cancers." (PMID 36675278, 2023). "Importantly, the amplicon often includes other cancer-relevant genes (e.g., CCND1 and GAB2), which might further cooperate with PAK1 in oncogenesis." (PMID 37830586, 2023). "Previous studies demonstrated that PAK1 could be crucial for PI3K/AKT and MEK/ERK signaling pathways, and blockage of PAK1 alleviates the tumor cells malignant behaviors via inhibiting ERK and AKT signaling activity in multiple malignant tumors." (PMID 34307365, 2021). "Thus, RAB7A could play a role in cancer cell proliferation and invasion regulating beta-catenin stability through AKT and PAK1." (PMID 34066419, 2021). "Therefore, the crosstalk between PAK1 and other pathways is also not negligible for the treatment of cancer." (PMID 32863957, 2020). "On the other-hand, PAK1 activation leads to the phosphorylation of S675 and S663 of β-catenin to stabilize β-catenin, and then to activate the transcription of target genes, such as MYC, CyclinD1, MMP, and PPARγ, to promote cancer cell proliferation and migration." (PMID 32863957, 2020). "However, under conditions of abundant chemotactic stimuli such as EGF and GABA, metastatic cancer cells demonstrated significantly increased extravasation rates, while PAK1 knockdown cell types did not respond to stimuli leaving extravasation rates unaltered." (PMID 30651600, 2019). "Hence, potential of PAK1 as a potential target for prognosis and molecularly targeted therapy in PESCC is worth considering in future studies looking for intervention of this dreadful carcinoma." (PMID 26023713, 2015). "The current study provides supportive evidences for the potential application of IPA-3 in HCC treatment and the specificity of IPA-3 in targeting PAK1, suggesting that IPA-3 is a potential therapeutic target for the treatment of HCC and may be more effective on the advanced cancers." (PMID 23894351, 2013). "An unbiased genetic screen for the events that protect cells from the toxicity of IPA3 may be warranted in order to uncover critical molecular events, either PAK1 dependent or not, that are triggered by this compound in cancer cells." (PMID 22869096, 2012). "To further determine whether LPA stimulates cancer cell migration in a PAK1-dependent manner, we investigated MDA-MB-231 cells migration using wound closure assay after transfecting these cells with the inactive mutant of PAK1 expression vector." (PMID 21209852, 2010). "Thus, it is worthwhile to explore whether the PAK1 and ERK signaling pathway is involved in LPA-induced cancer cell migration." (PMID 21209852, 2010). "In addition, subgroup meta-analysis based on cancer type, PAK1 nuclear localization and p-PAK1 expression could not be carried out with the existing data." (PMID 27027431, 2016). "PAK1, PAK2, and PAK4 have a higher expression level in most of cancer types, while other PAKs are not." (PMID 33796531, 2021).
cancer (continued). "Most slides from cancer-free tissue lacked expression of CCND1, CD44, CDH1, EGFR, ERBB2, KIT, keratins, NOTCH1, PAK1, PTGS2, SNAI1, and VIM but showed staining of MUC1, HIF1A, NKX2-1, SFTPC, and STAT3, which were also found in AdCa." (PMID 23028920, 2012). "In a clinical point of view, we confirmed that PAK1 is overexpressed in PDAC tissues by analyzing the TCGA-PAAD/GTEX GEPIA transcriptomic database while TRPM7 transcriptomic expression was not significantly different between cancer and non-cancer tissues." (PMID 40274768, 2025).